ATRX (ATRX chromatin remodeler)
Diseases named in the same sentence as ATRX in open-access papers (continued):
Sharing a sentence is not in itself a finding about the gene and the disease.
glioma (continued). "Given the relevance and frequency of ATRX mutations in high-grade glioma patients, we sought to validate the effect of BTK, STAT3, and RTK inhibitors in glioma cell lines derived from adult malignant glioma (MOG-G-UVW and U-251) and pediatric malignant glioma (SF188) patients." (PMID 35406561, 2022). "The role of ATRX/DAXX mutations in driving paediatric gliomas remains to be fully elucidated." (PMID 35382567, 2022). "Furthermore, this ATRX loss resulted in decreased T-cell-mediated glioma cell lysis, increased macrophage immune-suppressive M2-like polarization, and enhanced Treg tumor infiltration." (PMID 36212415, 2022). "IHC- and NGS-based testing for ATRX loss was concordant in 59 out of 60 glioma cases." (PMID 35372034, 2022). "Therefore, we explored the effect of combining TMZ and PDGFRi on ATRX-deficient high-grade glioma cells." (PMID 35406561, 2022). "Indeed, the detection of nuclear ATRX loss in an IDH-mutant glioma is sufficient for the diagnosis of an astrocytic lineage tumour without the need for 1p/19q codeletion analysis." (PMID 33293629, 2021). "In addition, despite using slightly different statistical cutoffs and models, several age-associated genomic features are identified by both studies, for example, the higher frequency of IDH1 and ATRX mutations in younger glioma patients." (PMID 33879792, 2021). "This suggests that ATRX loss in the presence of NF1 mutation may be sufficient to induce ALT in gliomas." (PMID 34069193, 2021). "Our study strongly suggests that in IDH-mutant gliomas, ATRX loss indicates astrocytic phenotype, ATRX retention, and H3K27me3 loss indicate oligodendroglial phenotype, while retained or non-conclusive ATRX and retained H3K27me3 mandate for 1p/19q codeletion testing." (PMID 34165590, 2021). "For instance, we have engineered ATRX-deficient gliomas, by injecting plasmids encoding SB transposase/firefly luciferase, plus other plasmids encoding for the desired genetic alterations located between IR/DR: shp53, NRASG12V, and shATRX, into the lateral ventricle of neonatal mice." (PMID 34168976, 2021). "IDH-mutant glioma with ATRX and TERT mutations was always associated with favorable survival." (PMID 34220791, 2021). "In addition, glioma with retained nuclear H3K27me3, loss of ATRX staining, and IDH1-R132H positivity can be predicted as 1p/19q non-codeleted glioma with a probability score of 0.9823." (PMID 34020723, 2021). "ATRX mutation constitutes the common genetic abnormalities in gliomas." (PMID 33678158, 2021). "Gliomas with wild-typeTERT promoters often present ATRX mutations to activate ALT." (PMID 34947936, 2021). "ATRX is a somatic mutation in the Alpha-Thalassemia/mental Retardation syndrome known as X-linked and may be reported in gliomas including GBM14 and is associated with a significantly better prognosis." (PMID 32111869, 2020).
glioma (continued). "However, GPR133 expression was higher in the infiltrative edge of gliomas with ATRX loss (Figure 4Cii)." (PMID 32642706, 2020). "Interestingly, G4 stabilization has been recently proposed as a strategy for the selective targeting of ATRX-deficient gliomas." (PMID 32183119, 2020). "Furthermore, “loss of ATRX in NF1 HGGs is unique when considered within the genetic contexts associated with ATRX mutations in sporadic gliomas,” in which they are typically associated with pediatric H3 K27M-mutant DMGs." (PMID 32582540, 2020). "Moreover, they indicate that, at least in this glioma-relevant context, increased G4s as a consequence of ATRX deficiency are insufficient to drive apoptosis or impact cellular proliferation." (PMID 30808951, 2019). "Moreover, low level of ZDHHC23 was also associated with 1p/19q co-deletion (p < 0.01), loss of TERT (p < 0.05), and mutated ATRX (p < 0.01) in the glioma tumors." (PMID 30658672, 2019). "ATRX loss can promote tumor growth and impair DNA repair in glioma." (PMID 32047515, 2019). "Here, the authors show that ATRX inactivation induces G-quadruplex formation, leading to genome-wide DNA damage, and the use of G-quadruplex stabilisers can be exploited therapeutically in ATRX deficient gliomas." (PMID 30808951, 2019). "One of the important chromatin chaperones is ATRX, which is frequently mutated in gliomas." (PMID 31311166, 2019). "Moreover, the vast majority of adult and pediatric gliomas with ATRX deficiency also contain mutant IDH and H3.3 genes, respectively, both of which have been shown to significantly and distinctively impact global epigenomic landscapes." (PMID 29535300, 2018). "In addition, recent work has suggested that downregulation of RAP1 and XRCC1 licenses IDH1-mutant glioma cells to engage the ALT mechanism after ATRX loss." (PMID 30226859, 2018). "To assess whether GNA13 might facilitate similar processes in ATRX-deficient human disease, we examined TCGA gene expression data for lower-grade glioma (LGG), focusing our analysis on those tumors harboring an IDH1 or IDH2 mutation." (PMID 29535300, 2018). "A previous study has shown that loss of wild-type ATRX is associated with tumor growth in glioma." (PMID 29617666, 2018). "ATRX mutation in adult glioma arises almost exclusively in the context of concurrent IDH mutation." (PMID 29535300, 2018).
glioma (continued). "There was a significantly positive relationship between TERT promoter mutations and ATRX activation (Χ2 = 27.289, P < 0.001) in gliomas, as supported by the previous studies that TERT promoter and ATRX mutations (usually caused ATRX inactivation) were mutually exclusive." (PMID 26556853, 2016). "In gliomas, ATRX mutation has been associated with a better prognosis in anaplastic gliomas." (PMID 26448930, 2015). "Other peaks, such as ATRX mutations in lower grade glioma or ARID1A mutations in endometrial cancer and stomach adenocarcinoma may represent other points of entry for therapeutic intervention." (PMID 25484917, 2014). "Piloid features in a setting of high-grade glioma may harbor ATRX mutation and CDKN2A deletion." (PMID 40277798, 2025). "Thus, testing for the ATRX mutation may have utility in the clinical management of high-grade glioma patients." (PMID 38633919, 2024). "Inhibitors targeting SIRT2 induce epigenome reprogramming in ATRX-deficient glioma models by modifying H3K27ac and H4K16ac marks on chromatin and causing genome-wide changes via enhancer-associated modifications, promoting senescence in the ATRX-deficient glioma model system." (PMID 39479502, 2024). "Interestingly, although both H3.3 mutations alter the size and number of PML bodies relative to WT H3.3, the specific effects vary depending on the point mutation (G34R, K27M), the presence of additional mutations (e.g., ATRX), and the cell type (human glioma, mouse ES cells)." (PMID 38066546, 2023). "Our results regarding the frequency of PTEN and RAS–MAPK pathway alterations suggest that this approach may have a rationale in ATRX-deficient IDH-wildtype adult gliomas and ATRX loss could be a potential marker to predict responder cases to immunotherapeutic interventions." (PMID 37891325, 2023). "Therefore, ATRX mutations may consequently lead to an abnormal telomeric phenotype, which has been proven in glioma." (PMID 35860263, 2022). "In addition, ATRX-null glioma cells are more susceptible to temozolomide than ATRX-WT." (PMID 34069193, 2021). "In our exploration, we found out that by combining IDH1 mutation with ATRX mutation, gliomas in the low-risk group could be further divided into three subtypes: LowRisk_IDH1wt, LowRisk_IDH1mut/ATRXmut and LowRisk_IDH1mut/ATRXwt with obvious survival difference." (PMID 34093830, 2021). "Furthermore, in adult high-grade gliomas, inactivating mutations in ATRX are mutually exclusive with activating mutations in the TERT promoter, providing genetic evidence that ATRX loss contributes to telomere maintenance via the ALT phenotype in this cancer subtype." (PMID 30226859, 2018). "Moreover, our analysis of human tissue samples and multiple primary GSCs revealed that this molecular mechanism might also be operative in ATRX-deficient gliomas." (PMID 29535300, 2018).
glioma (continued). "For example, in a diffuse glioma without morphological evidence of oligodendroglioma, IDH1 and ATRX analysis may be carried out initially, but would 1p/19q analysis still need to be performed in gliomas with ATRX mutation or loss of protein expression (ie, molecular evidence of astrocytoma)?" (PMID 24990071, 2014). "One of the DEGs, developmentally regulated GTP-binding protein 2 (DRG2), was a particularly striking outlier, and was consistently downregulated in ATRX-mutant low grade glioma." (PMID 39921567, 2025). "ATRX knockout has been shown to suppress malignant behaviors in glioma cells and plays a critical role in regulating DNA damage repair through the ATM signaling pathway." (PMID 40282990, 2025). "First, we validated the association between ATRX and SETD2 mutations using the PeCan dataset for paediatric glioma (both high-grade and low-grade)." (PMID 39921567, 2025). "Unexpectedly, a significant proportion of ATRX-altered gliomas (18% in the TCGA cohort and 28% in our local cohort) were not classic IDH-mutant astrocytomas or histone-mutant gliomas." (PMID 41422096, 2025). "Studies in telomerase-positive glioma cells have shown that ATRX localizes to subtelomeric regions, where its knockdown reduces cohesin occupancy." (PMID 40437074, 2025). "ATRX loss and OLIG2 overexpression support glioma stemness and chromatin remodeling, while MGMT activity influences chemoresistance." (PMID 40282990, 2025). "Inactivating mutations in ATRX have been shown to disrupt immune signaling pathways, such as promoting immunosuppressive mechanisms in IDH1-mutant gliomas and impairing cGAS-STING signaling in sarcomas." (PMID 40495762, 2025). "To address this, we analyzed ATRX-altered gliomas from TCGA (N = 539 tumors, 587 alterations) and a local cohort of 100 diffuse gliomas." (PMID 41422096, 2025). "For instance, DRG2 emerged as the top contributor in classification of ATRX alterations in lower-grade gliomas and was significantly downregulated in ATRX mutant tumours." (PMID 40775769, 2025).
glioma (continued). "Mutations in the ATRX gene can result in ATR-X syndrome or in many types of cancer, particularly in glioma." (PMID 40429944, 2025). "ATRX showed one of the strongest transcriptional signatures in lower-grade gliomas (LGG), with the DRG2 gene emerging as the top feature in classification." (PMID 40775769, 2025). "Here, we have demonstrated that for ALT-pathway activity in glioma (and possibly other ALT-cancer types), the proximal genetic causation is ATRX loss, whilst the evolutionary causation can be accumulation of ROS." (PMID 39921567, 2025). "This is consistent with findings in glioma models identifying suppression of SOX2 expression with ATRX depletion." (PMID 41380652, 2025). "It is worth noting that some studies have proposed that IDH and ATRX alterations are more common in low-grade gliomas." (PMID 38315329, 2024). "In gliomas, telomerase is activated mainly by a mutation in the TERT promoter, while ALT activation is usually associated with an ATRX mutation." (PMID 38674026, 2024). "In most gliomas, ATRX deletion in combination with IDH mutation leads to immunosuppression, whereas IDH-mutant, ATRX-mutant astrocytomas exhibit greater immune cell infiltration than IDH-mutant, ATRX wild-type oligodendrogliomas." (PMID 39479502, 2024). "As a chromatin remodeling protein, ATRX plays an important role in double-stranded break repair in glioma." (PMID 38898533, 2024). "In glioma, miR-1269a has been identified as a regulator that targets ATRX, promoting cell proliferation and invasion." (PMID 38279330, 2024). "The association between ATRX and ABCG2 levels in brain tumors, particularly in gliomas, highlights the complex interplay of genetic alterations and drug resistance mechanisms that influence tumor behavior and therapeutic outcomes." (PMID 38542090, 2024). "ATRX and DAXX act as tumor suppressor proteins and are typically mutated in cells exhibiting ALT-like characteristic gliomas." (PMID 39479502, 2024). "Using a CRISPR/Cas9 approach, we generated single cell Atrx-KO clones—KO-A and KO-B—isolated from the murine CT2A glioma cell line and a polyclonal ATRX-KO derivative of the human M059J glioma cell line, along with corresponding controls." (PMID 38272925, 2024). "There are several potential mechanisms underlying the implications of the interplay between ATRX mutation status and ABCG2 expression in gliomas." (PMID 38542090, 2024). "Their risk-model holds potential for diagnostic applications, prognosis prediction, and therapeutic planning in ATRX-wt glioma patients." (PMID 39513108, 2024).